BCR (BCR activator of RhoGEF and GTPase)
Diseases named in the same sentence as BCR in open-access papers (continued):
Sharing a sentence is not in itself a finding about the gene and the disease.
nephrolithiasis (2 papers, 2022). The presence of a calculus in the pelvis of the kidney; this is most often composed of mineral salts and proteins. "A recent meta-analysis identified 20 nephrolithiasis-associated loci, including CYP24A1, DGKD, DGKH, WDR72, GPIC1, and BCR locus which were predicted to affect vitamin D metabolism and calcium-sensing receptor signaling respectively." (PMID 35439979, 2022). "SNP rs13054904 located ∼110 kb upstream of BCR, which was identified to be associated with nephrolithiasis in British population but not Japanese population through GWAS." (PMID 35910217, 2022).
neutropenia (2 papers, 2024). A decrease in the number of neutrophils found in the blood. "We eventually restarted imatinib due to a rising BCR-ABL:ABL ratio, but fortunately found that the patient tolerated dual TKI therapy very well with only mild neutropenia and bruising." (PMID 39583986, 2024).
oligodendroglioma (2 papers, 2023 to 2024). A well-differentiated (WHO grade II), diffusely infiltrating neuroglial tumor, typically located in the cerebral hemispheres. "One GBM, IDH-wt with the BCR::NTRK2 fusion, in patient #12 (54 y/M) contained uniform round cells with a clear cytoplasm, resembling those of oligodendroglioma." (PMID 39014476, 2024). "The second case (#27), harboring a BCR::NTRK2 fusion, showed a biphasic tumor with an oligodendroglioma‐like and piloid cytology (without Rosenthal fibers or eosinophilic granular bodies) and an angiocentric pattern." (PMID 37349135, 2023).
Parkinson disease (2 papers, 2022 to 2025). A progressive degenerative disorder of the central nervous system characterized by loss of dopamine producing neurons in the substantia nigra and the presence of Lewy bodies in the substantia nigra and locus coeruleus. "Her past medical history was remarkable for Parkinson’s disease, thyroid cancer treated with thyroidectomy and radioactive iodine, and chronic phase, BCR::ABL‐positive CML in the last 15 years." (PMID 41473461, 2025).
periodontitis (2 papers, 2020 to 2021). An acute or chronic inflammatory process that affects the tissues that surround and support the teeth. "The strong associations among ISG20, ESRP1 and activated B cell, BCR signaling pathway, and HLA-DOB in periodontitis were first identified in our study." (PMID 34285922, 2021). "Our study depicted the correlations among RBPs and immune microenvironment and biological reactions in periodontitis, with strong correlations of the RBPs ISG20 and ESRP1 with activated B cell infiltration, BCR signaling activation, and HLA-DOB expression." (PMID 34285922, 2021). "Correlation analysis demonstrated that the most positively correlated immune pathway-RBP pair is BCR signaling pathway (B cell receptor signaling pathway) and ISG20, with higher activities of both in periodontitis." (PMID 34285922, 2021).
schizophrenia (2 papers, 2009 to 2013). A major psychotic disorder characterized by abnormalities in the perception or expression of reality. "The top ranked pathways with significant p-value associated with BA22 and Roessler liver 2 sample include the PDGFR-beta signaling pathway, the ErbB1 downstream signaling and BCR signaling pathway which indicates common pathways for schizophrenia and cancer." (PMID 24564241, 2013).
systemic mastocytosis (2 papers, 2015 to 2025). Systemic mastocytosis (SM) comprises a heterogeneous group of rare acquired and chronic hematological malignancies that are related to an abnormal proliferation of mast cells in tissue, including bone marrow, with or without skin involvement. "Taken together, our results point to SETD2/H3K36me3 deficiency as a mechanism, already identified by our group in systemic mastocytosis, that is reversible, druggable, and BCR::ABL1‐independent, able to cooperate with BCR::ABL1 in driving genetic instability in CML." (PMID 40275711, 2025).
systemic sclerosis (2 papers, 2020 to 2021). A chronic disorder, possibly autoimmune, marked by excessive production of collagen which results in hardening and thickening of body tissues. "Accordingly, the new generation of breakpoint cluster region (BCR)-ABL inhibitors (Dasatinib and Nilotinib) is currently being used for the treatment of systemic sclerosis." (PMID 32466585, 2020).
Waldenström macroglobulinaemia (2 papers, 2015 to 2024). "Similarly, DARA modulates BCR and AKT‐associated signalling in Waldenström macroglobulinaemia." (PMID 39364393, 2024).
X-linked agammaglobulinemia (2 papers, 2020 to 2021). X-linked agammaglobulinemia (XLA) is a clinically variable form of isolated agammaglobulinemia, an inherited immunodeficiency disorder (see this term), and is characterized in affected males by recurrent bacterial infections during infancy. "Fourth, genetic mutations of non-X linked agammaglobulinemia encoding for pre-BCR and/or BCR complex (such as IGHM, CD79a, CD79b, and IGLL1 genes) and for activating mTOR signaling (such as PI3KD and PIK3R1 genes)." (PMID 33013854, 2020).
AA amyloidosis (1 paper, 2015). Secondary amyloidosis is a form of amyloidosis, that complicates chronic inflammatory disorders (mainly rheumatoid arthritis) and is characterized by the aggregation and deposition of amyloid fibrils composed of serum amyloid A protein, an acute phase reactant. "In vitro HGAL enhances BCR signaling by binding and increasing Syk activation, in vivo older HGAL transgenic animals progressively developed polyclonal lymphoid hyperplasia and reactive AA amyloidosis, these finding suggests that GCET2 may play a role in humoral immune responses." (PMID 25502083, 2015).
acute erythroleukemia (1 paper, 2025). "Given that the K562 cell line was derived from a CML patient who developed acute erythroleukemia, we hypothesized that the BCR::ABL1-SPHK1-S1P regulatory axis might be erythroid-specific." (PMID 40221405, 2025).
Anxiety (1 paper, 2023). Intense feelings of nervousness, tension, or panic often arise in response to interpersonal stresses. "BCR between RP and 2015 as well as late BCR between 2015 and 2020 was associated with higher levels of PC anxiety in 2020 (beta: 0.054; p = 0.002 and beta: 0.054; p < 0.001, respectively)." (PMID 36254563, 2023). "Interestingly, an earlier BCR (i.e., between RP and initial assessment) was only associated with PC anxiety, but not with PSA anxiety." (PMID 36254563, 2023).
Arterial thrombosis (1 paper, 2025). The formation of a blood clot inside an artery. "However, there is little evidence that proper management of lipid metabolism in patients receiving BCR::ABL1 TKIs will stop arterial thrombosis and prevent vascular occlusive events." (PMID 41473461, 2025).
brain ischemia (1 paper, 2017). Diminished or absent blood supply to the brain caused by obstruction (thrombosis or embolism) of an artery resulting in neurologic damage. "Fyn associates with NMDARs, and its activity is implicated in the pathogenesis of brain ischemia; hence, both proteins are likely candidates for mediating the NMDAR-dependent deactivation of BCR in response to OGD." (PMID 29046349, 2017).
Cachexia (1 paper, 2022). Severe weight loss, wasting of muscle, loss of appetite, and general debility related to a chronic disease. "B cells from patients with cachexia showed lower expression of MHC-II molecules (HLA-DRB5, HLA-DQA2) and higher expression of the immunoglobulins (IGHG2, IGHG3, IGKC), and genes involved in BCR signaling." (PMID 36376273, 2022).
chordoma (1 paper, 2023). Chordomas are rare malignant tumors arising from embryonic remnants of the notochord in axial skeleton. "Primary chordomas, on the other hand, were enriched with dendritic cells (DCs) and antigen‐presenting cancer‐associated fibroblasts (apCAFs) with a strong antigen‐presenting signature, while plasma cells and B‐cell receptor (BCR) clonotypes were less abundant in recurrent chordomas." (PMID 37784253, 2023). "To obtain an understanding of the differences in single cells between primary and recurrent chordomas, we performed single‐cell RNA sequencing and T‐cell/B‐cell receptor (BCR) sequencing." (PMID 37784253, 2023). "We found that there were fewer BCR clonotype of B cells in recurrent chordomas, although B cells were enriched in recurrent chordomas." (PMID 37784253, 2023). "There were fewer plasma cells and BCR clonotypes in recurrent chordomas." (PMID 37784253, 2023). "There were also fewer BCR clonotypes of plasma cells in recurrent chordomas." (PMID 37784253, 2023).
chronic GVHD (1 paper, 2023). "Thus, the current BCR::ABL1 level less than 0.06% in patients with chronic GvHD predicts low risk of relapse." (PMID 37798335, 2023). "Thus, since day + 100 after allo-HSCT the patients with chronic GvHD and current BCR::ABL1 level equal to or higher than 0.06% can be classified as high risk of relapse." (PMID 37798335, 2023). "At the same time, patients without chronic GVHD after allo-HSCT should be classified as high risk with any level of BCR::ABL1." (PMID 37798335, 2023). "BCR::ABL1 level before and after allo-HSCT, prediction moment, and chronic GvHD had the highest value in the model." (PMID 37798335, 2023). "At the same time, if the patient had no chronic GVHD after allo-HSCT till the prediction moment, he should be classified to a high risk group at any BCR::ABL1 level." (PMID 37798335, 2023). "According to the map, depending on the presence or absence of chronic GVHD and the definite levels ​​of the BCR::ABL1, the patient can be assigned to a group of high (the relapse risk is over 20%) or low (the relapse risk is less 20%) risk of relapse." (PMID 37798335, 2023).
chronic heart failure (1 paper, 2025). "In the context of chronic heart failure, an increased BCR has been linked to heightened mortality." (PMID 40110543, 2025).
chronic leukemia (1 paper, 2024). A slowly progressing leukemia characterized by a clonal (malignant) proliferation of maturing and mature myeloid cells or mature lymphocytes. "The gold standard for treatment in chronic leukemias, and the most promising agent for PH treatment among the BCR-ABL group, is imatinib." (PMID 39684570, 2024).
Chylothorax (1 paper, 2024). The presence of chyle in the thoracic cavity. "Although bosutinib has a similar mechanism of action as dasatinib, serving as a BCR-ABL tyrosine kinase inhibitor, it has a unique feature that decreases the risk of development of a chylothorax in this patient population." (PMID 39360083, 2024).
Cirrhosis (1 paper, 2025). A chronic disorder of the liver in which liver tissue becomes scarred and is partially replaced by regenerative nodules and fibrotic tissue resulting in loss of liver function. "Our study investigated the association between BCR and all-cause mortality in critically ill cirrhosis patients using a multivariate Cox regression model." (PMID 40110543, 2025). "This study explored the association between BCR and mortality in critically ill cirrhosis patients." (PMID 40110543, 2025). "The association between BCR and all-cause mortality in critically ill patients with cirrhosis." (PMID 40110543, 2025). "We employed a forest plot to illustrate the relationship between BCR and mortality at 180 and 365 days in critically ill cirrhosis patients with varying clinical characteristics." (PMID 40110543, 2025). "Our research highlights BCR’s potential as a prognostic marker for cirrhosis, especially in elderly patients." (PMID 40110543, 2025). "Our study supports the role of BCR as a prognostic indicator in cirrhosis patients, aligning with previous findings." (PMID 40110543, 2025). "The study categorized severe hepatic cirrhosis patients into four groups (Q1 to Q4) according to BCR quartiles and examined the baseline characteristic differences among these groups." (PMID 40110543, 2025). "However, the relationship between BCR and mortality in critically ill patients with cirrhosis is unclear, The purpose of this study is to explore this question." (PMID 40110543, 2025). "Baseline characteristics of the cirrhosis population according to BCR quartiles." (PMID 40110543, 2025). "Elevated BCR may indicate a poorer prognosis in older patients with cirrhosis." (PMID 40110543, 2025).
combined immunodeficiency (1 paper, 2025). A broad classification of inherited disorders presenting at birth that affect both the cell-mediated and humoral aspects of the immune response. "Severe defects of V(D)J recombination, such as complete RAG1 or RAG2 deficiency, prevent proper rearrangement and recombination of the TCR and BCR genes and thus result in severe combined immunodeficiency (SCID), which impacts both T and B cell lineages." (PMID 41607487, 2025).
cryoglobulinemia (1 paper, 2015). Cryoglobulinemia is a type of vasculitis that is caused by abnormal proteins (antibodies) in the blood called 'cryoglobulins.' At cold temperatures, these proteins become solid or gel-like, which can block blood vessels and cause a variety of health problems. "The marginal zone like IgM+ CD21lo CD27+ B cells in HCV infected patients with cryoglobulinemia show reduced calcium flux in response to BCR stimulation." (PMID 26649443, 2015). "Decreased BCR signaling has also been observed in CD21+ CD27+ B cells of HCV donors with cryoglobulinemia." (PMID 26649443, 2015). "In HCV infection with cryoglobulinemia, CD21lo CD27+ B cells have decreased mobilization of calcium after BCR stimulation." (PMID 26649443, 2015).
delirium (1 paper, 2022). A disorder characterized by confusion; inattentiveness; disorientation; illusions; hallucinations; agitation; and in some instances autonomic nervous system overactivity. "The BCR has been reported as a marker for dehydration and is thought to be associated with delirium." (PMID 36078999, 2022). "Specifically, BCR > 18 was suggested as an independent risk factor for delirium." (PMID 36078999, 2022). "In the Hypoactive delirium motor subtype group, the BCR was positively correlated with delirium prevalence." (PMID 36078999, 2022). "The notable finding of this study was that the relationship between the BCR and delirium occurrence was only exhibited in patients with the hypoactive subtype." (PMID 36078999, 2022). "We analyzed the occurrence of delirium in each decile group as defined by the BCR in the whole set of patients." (PMID 36078999, 2022). "We investigated whether BCR could be used to predict the occurrence and motor subtype of delirium in ICU patients through a retrospective cohort study that included 7167 patients (50 years or older) admitted to the ICU." (PMID 36078999, 2022). "Therefore, it is worth examining the potential significance of the BCR in the prediction and early detection of delirium and other cognitive problems." (PMID 36078999, 2022). "In addition, to examine the specific relationship between the BCR and each delirium motor subtype, we analyzed the predictive power of the BCR for each motor subtype." (PMID 36078999, 2022). "We hypothesized that the BCR was associated with the hypoactive subtype of delirium but not with the hyperactive or mixed subtypes." (PMID 36078999, 2022). "Thus, the extent of the relationship between the BCR and delirium, as well as the optimal BCR cutoff value for predicting delirium, remain unclear." (PMID 36078999, 2022). "A previous study that identified BCR > 18 as a risk factor for delirium could not be replicated." (PMID 36078999, 2022).
dermatomyositis (1 paper, 2023). Dermatomyositis (DM) is a type of idiopathic inflammatory myopathy characterized by evocative skin lesions and symmetrical proximal muscle weakness. "In this prospective exploratory study, we identified expanded BcR clones in muscle tissues of IIM patients prior to treatment, which confirms a report on treatment-naive dermatomyositis and polymyositis patients." (PMID 36321862, 2023).
endometriosis (1 paper, 2022). The growth of functional endometrial tissue in anatomic sites outside the uterine body. "In the immune response gene concentration, antimicrobials, BCR signaling pathway, chemokine receptors, chemokines, cytokines, interleukins, interleukin receptors, TGF-β family members, and TNF family members were highly expressed in endometriosis." (PMID 36532015, 2022).
Eosinophilic Disorders (1 paper, 2026). "The 2023 ICC of Eosinophilic Disorders offers updated and more precise guidance for distinguishing MLN-eo-TK (especially those presenting as ALL) from BCR::ABL1-like B-ALL and de novo T-ALL." (PMID 41530508, 2026).
epilepsy (1 paper, 2025). A brain disorder characterized by episodes of abnormally increased neuronal discharge resulting in transient episodes of sensory or motor neurological dysfunction, or psychic dysfunction. "Notably, BCR was effectively utilized to visualize biomolecular changes in a PTZ‐induced zebrafish epilepsy model, capturing dynamic fluctuations of these biomarkers associated with oxidative stress and energy metabolism." (PMID 39887673, 2025).
esthesioneuroblastoma (1 paper, 2025). "This review compared the results after OpS ± E-ass, stratified relative to BCR/TCR ± E-ass, CFR ± E-ass, and TFR ± E-ass, and ES for esthesioneuroblastoma selecting 144 reports including 1,434 patients published from 1990 to 2023." (PMID 40502638, 2025).
exomphalos (1 paper, 2025). "Three cases of exomphalos were also found in our cohort in association with imatinib (cases i, v, x), and none were observed with other BCR::ABL1 TKIs or anticancers." (PMID 40442861, 2025).
eye inflammation (1 paper, 2024). "Whether this CD8+ NK subset (i.e., cluster 10) may directly contribute to eye inflammation in BCR-UV, remains to be determined." (PMID 39085199, 2024).
Gynecomastia (1 paper, 2024). Abnormal development of large mammary glands in males resulting in breast enlargement. "Since imatinib is an inhibitor of tyrosine kinase BCR-ABL, c-Kit, PDGFR, and tyrosine kinase subclass 3 family, it is predictable that patients might experience signs and symptoms related to reduced androgen production like gynecomastia." (PMID 38398181, 2024).
hereditary angioedema (1 paper, 2024). Hereditary angioedema (HAE) is a genetic disease characterized by the occurrence of transitory and recurrent subcutaneous and/or submucosal edemas resulting in swelling and/or abdominal pain. "Other group A proteins mapped to pathways of defective factor XII and defective SERPING1, which cause hereditary angioedema, CD22 (receptor predominantly restricted to B cells)-mediated BCR (B-cell receptors) regulation, and the recycling of bile acids and salts." (PMID 39057787, 2024).
HIV-1 infection (1 paper, 2013). The type species of lentivirus and the etiologic agent of acquired immunodeficiency syndrome (AIDS). "For instance, it may be that the development of such antibodies during natural HIV-1 infection depends on the emergence of particular Env clones in certain HIV-infected subjects; clones with particular structural characteristics that allow them to engage the germline BCR form of bNAb to the CD4-BS." (PMID 23300456, 2013).
hookworm infections (1 paper, 2024). "Indeed, the BCR isolate is profoundly resistance to the 3 classes of anthelmintic that are currently used for treatment of canine and zoonotic hookworm infections, which will complicate treatment of hookworm infections should they become widespread." (PMID 38163962, 2024).
hydronephrosis (1 paper, 2023). Collection of urine in the renal pelvis that results in dilatation of the renal pelvis and calyces. "Strikingly, we observed high MC counts in the BM and kidney as well as hydronephrosis in some recipients, demonstrating the cell-autonomous properties of the BCR::ABL1 positive donor cells." (PMID 37161070, 2023). "For this mouse model, we observed uni- or bilateral hydronephrosis in BCR::ABL1 positive mice driven by urinary obstruction due to myeloid infiltration within the renal pelvis and ureters." (PMID 37161070, 2023).